NEFL (neurofilament light chain)
Diseases named in the same sentence as NEFL in open-access papers (continued):
Sharing a sentence is not in itself a finding about the gene and the disease.
memory impairment (5 papers, 2022 to 2025). "We further examined the neural correlates of memory impairments through voxel-based morphometry (VBM) analysis of structural MRI data, and explored associations with plasma neurofilament light chain (NfL) levels, a biomarker of neuroaxonal damage." (PMID 41172859, 2025).
neurosyphilis (5 papers, 2020 to 2026). Infection of the brain or spinal cord by Treponema pallidum. "Serum neurofilament light chain (NfL), a biomarker of axonal injury, is markedly elevated in patients with neurosyphilis and shows a positive correlation with NfL levels in CSF." (PMID 41602984, 2026).
optic neuritis (5 papers, 2020 to 2025). Optic neuritis is inflammation of the optic nerve, the nerve that carries the visual signal from the eye to the brain.The conditionmay cause sudden, reduced vision in the affected eye(s). "Increased abundance of inflammatory cytokines (e.g. tumour necrosis factor-α) and the axonal marker (neurofilament light chain) in the CSF have been proposed as early biomarkers to diagnose MS and/or optic neuritis in patients." (PMID 35644788, 2022).
renal failure (5 papers, 2022 to 2025). "This study compares the levels of neuron specific enolase (NSE), brain-derived neurotrophic factor (BDNF), neurofilament light chain (NfL), and circulating plasma extracellular vesicles (EVs) in kidney-failure patients before KT and at a two-year follow up." (PMID 37047601, 2023).
subarachnoid hemorrhage (5 papers, 2020 to 2024). A serious neurological disorder characterized by intracranial hemorrhage into the subarachnoid space. "In humans after subarachnoid haemorrhage, haemoglobin in cerebrospinal fluid was associated with neurofilament light chain, a marker of neuronal damage." (PMID 32346673, 2020).
cerebral malaria (4 papers, 2022 to 2024). A sequestration of Plasmodium falciparum in the brain, which can cause coma and/or seizures. "Ubiquitin C-terminal hydrolase-L1 and neurofilament-light chain levels are elevated in paediatric cerebral malaria and severe malarial anaemia." (PMID 38075948, 2023).
hip fracture (4 papers, 2021 to 2026). Traumatic or pathological injury to the hip in which the continuity of either the femoral head, femoral neck, intertrochanteric or subtrochanteric regions is broken. "In the total hip fracture cohort, CSF levels of cell-free DNA and neurofilament light chain were significantly correlated after adjusting for age and sex (r = 0.441, P < 0.001)." (PMID 39737468, 2025).
HIV dementia (4 papers, 2006 to 2022). "Cerebrospinal fluid (CSF) neurofilament light chain (NFL) level is a biomarker of CNS injury in HIV dementia." (PMID 35733470, 2022).
psoriasis (4 papers, 2021 to 2024). An autoimmune condition characterized by red, well-delineated plaques with silvery scales that are usually on the extensor surfaces and scalp. "Serum concentrations of fatty acid-binding protein 7 (FABP-7), glutamic acid (GA) and neurofilament light chain (NFL), which have been hardly studied in psoriasis before, were measured by ELISA before and after 12 weeks of treatment with acitretin or methotrexate." (PMID 35566558, 2022).
secondary progressive MS (4 papers, 2019 to 2025). "The aim of this study was to characterize the pharmacokinetics and -dynamics as well as neurodestruction marker serum neurofilament light chain (sNfL) in patients with RRMS and secondary progressive MS (SPMS) stopping NAT in correlation to clinical data." (PMID 33935948, 2021).
sleep disorder (4 papers, 2022 to 2024). A change from the patient's baseline sleeping pattern, in the hours slept and/or an alteration/dysfunction in the stages of sleep. "Some studies revealed the potential utilization of neurofilament light chain (NfL) and glial fibrillary acidic protein (GFAP) concentration levels as biomarkers of sleep disorder and daytime drowsiness, as well as their roles in predicting decline in neurodegeneration and cognitive performance." (PMID 38421124, 2024).
viral infection (4 papers, 2017 to 2025). "Interestingly genes RASD1 NEFL, CALCA and PIK3R5 are more involved in cell signalling and proliferation, possibly reflecting the impact of viral infection on cell-cycle." (PMID 28406989, 2017).
asthma (3 papers, 2023 to 2025). "Neural mechanisms are important in asthma, and serum neurofilament light chain (sNfL) is a biomarker of neuronal damage." (PMID 40689320, 2025). "A recent study identified a significant increase in astrocytes activation markers, as GFAP (Glial Fibrillary Acid protein) and NfL (Neurofilament Light Chain), which was significantly related to asthma severity." (PMID 36983294, 2023).
astrocytoma (3 papers, 2015 to 2024). "Our study indicated that NEFL is a new target molecule of miR-381 and is downregulated in astrocytoma." (PMID 25605243, 2015).
breast tumors (3 papers, 2012 to 2023). "NEFL mRNA expression level was down-regulated in lymph node metastases compared to their paired primary tumors and was lower in the primary breast tumors of patients with positive lymph nodes than in patients with negative lymph nodes." (PMID 22319610, 2012). "Immunofluorescence of Neurofilament Light Chain (NF-L, neural fibers), Tyrosine Hydroxylase (TH, catecholamine nerves) and synaptophysin (SYP) confirm the presence of neural signals in both human and mouse breast tumors." (PMID 37463926, 2023). "It was reported that methylation-mediated inactivation of NEFH, NEFL or NEFM was common in primary breast tumors compared to normal breast tissues and correlated with clinical features of disease progression." (PMID 34001208, 2021).
cataract (3 papers, 2014 to 2024). Partial or complete opacity of the crystalline lens of one or both eyes that decreases visual acuity and eventually results in blindness. "Furthermore, a previous study of mice that overexpressed neurofilament light chain reported the development of cataracts, although further characterisation was not undertaken." (PMID 24764192, 2014).
Gaucher disease (3 papers, 2020 to 2022). Gaucher disease (GD) is a lysosomal storage disorder encompassing three main forms (types 1, 2 and 3), a fetal form and a variant with cardiac involvement (Gaucher disease - ophthalmoplegia - cardiovascular calcification or Gaucher-like disease). "Clinical evaluation of ApoE and neurofilament light chain (Nf-L) as biomarkers of Gaucher disease (GD)-associated neurodegeneration." (PMID 35972072, 2022).
Impaired glucose tolerance (3 papers, 2021 to 2025). An abnormal resistance to glucose, i.e., a reduction in the ability to maintain glucose levels in the blood stream within normal limits following oral or intravenous administration of glucose. "An earlier study reported higher blood NFL (also known as NEFL) mRNA levels in people with impaired glucose tolerance and/or impaired fasting glucose and peripheral neuropathy than those without." (PMID 36472640, 2023). "Recently, another study showed that the mRNA levels of NfL (also known as NEFL) in the blood of individuals with impaired glucose tolerance displayed a positive correlation with the severity of DPN." (PMID 34480211, 2021).
MELAS (3 papers, 2021 to 2024). "The objective of this study was to investigate the serum neurofilament light chain (NfL) as a novel biomarker of neurological dysfunction in MELAS." (PMID 33479417, 2021).
periodontitis (3 papers, 2022 to 2024). An acute or chronic inflammatory process that affects the tissues that surround and support the teeth. "The association between serum neurofilament light chain (sNfL) and periodontitis remains unclear, and there is a need to examine the contribution of serum albumin (SA) in this association." (PMID 38864919, 2024).
prostate carcinoma (3 papers, 2016 to 2022). A carcinoma that arises from epithelial cells of the prostate gland. "Overall, we show that NEFL expression occurs in a subset of prostate cancer cells with neuroendocrine-like phenotype that is associated with aggressive prostate cancer and siRNA silencing of NEFL inhibits the migration and invasion potential of PC3-ML2 cells." (PMID 36345474, 2022). "To further understand the role of NEFLin prostate cancer pathogenesis, we have determined the expression profile of NEFL gene in a panel of 10 cell lines that include a normal epithelial prostate cancer cell line and nine prostate cancer cell lines with different malignancy phenotypes." (PMID 36345474, 2022).
Wolfram syndrome (3 papers, 2021 to 2026). Wolfram syndrome (WS) also known as DIDMOAD, is a neurodegenerative disorder characterized by type I diabetes mellitus (DM), diabetes insipidus (DI), sensorineural deafness (D), bilateral optical atrophy (OA) and neurological signs. "Biomarkers for neurodegeneration, such as neurofilament light chain and myelin basic protein, have been assessed in patients with Wolfram syndrome before." (PMID 34185708, 2021).
amnesia (2 papers, 2025). Pathologic partial or complete loss of the ability to recall past experiences ( AMNESIA, RETROGRADE) or to form new memories ( AMNESIA, ANTEROGRADE). "We aimed to determine whether transient global amnesia (TGA) is associated with alterations in central nervous system (CNS) injury biomarkers—serum neurofilament light chain (sNfL) and serum glial fibrillary acidic protein (sGFAP)." (PMID 40141275, 2025).
Arthritis (2 papers, 2024 to 2025). Inflammation of a joint. "In summary, this nationally representative study identifies a novel association between serum neurofilament light chain levels and the presence of arthritis, encompassing osteoarthritis, rheumatoid arthritis, psoriatic arthritis, and other joint disorders." (PMID 40725940, 2025). "Relationship between serum neurofilament light chain levels and arthritis." (PMID 40725940, 2025).
autism spectrum disorder (2 papers, 2022 to 2023). A spectrum of developmental disorders that includes autism, and Asperger syndrome. "This study aimed to investigate serum neurofilament light chain (NFL), and TSP1 levels of patients with autism spectrum disorder (ASD) compared to typically developing (TD) children." (PMID 36326357, 2022).
Cirrhosis (2 papers, 2023 to 2025). A chronic disorder of the liver in which liver tissue becomes scarred and is partially replaced by regenerative nodules and fibrotic tissue resulting in loss of liver function. "Recently, glial fibrillary acidic protein (GFAP), an intermediate filament found in astrocytes, and especially neurofilament light chains (NfL), an important structural protein found in neurons, have emerged as promising biomarkers for HE in patients with cirrhosis." (PMID 41200277, 2025).
deafness (2 papers, 2021 to 2023). An inherited or acquired condition characterized by the complete loss of the ability to hear from one or both ears. "The current work found a series of DEGs related to sensory epithelial development and cytoskeleton organization through functional enrichment and PPI network analysis, including ATOH1, VIM, PRPH and NEFL, which may be involved in the pathogenesis of ELMOD3 causing deafness." (PMID 37708136, 2023).
dermatitis (2 papers, 2022 to 2024). An inflammatory process affecting the skin. "Also following 20 Gy, the neurofilament light chain (NFL) protein, a biomarker of neurodegeneration, was increased in the hippocampus at the time of peak dermatitis." (PMID 38891920, 2024).
hypoxic-ischemic encephalopathy (2 papers, 2022 to 2025). "Neurofilament light Chain (NfL) is a promising brain injury biomarker which may assist diagnosis and prognostication in hypoxic-ischemic encephalopathy (HIE)." (PMID 36699314, 2022).
pancreatic cancer (2 papers, 2019 to 2022). "In summary, our single-cell RNA sequencing and bioinformatics analysis identified several highly variable genes including IFI27, KRT18, KRT19, MMP1, MMP3, and NEFL, whose expression is associated with a shorter overall survival of pancreatic cancer patients." (PMID 36010660, 2022).
SMA type 1 (2 papers, 2023 to 2024). "Neurofilament light chain (NfL) has been proposed as a biomarker reflecting disease severity and therapy response in children with spinal muscular atrophy type 1 and 2 (SMA1 and 2)." (PMID 38162454, 2023).
spinal cord disease (2 papers, 2025 to 2026). "This study evaluated serum neurofilament light chain (NfL) as a biomarker in 46 healthy and 76 dogs with spinal cord diseases, including intervertebral disc herniation (IVDH), syringomyelia (SM), fibrocartilaginous embolism, and acute non-compressive nucleus pulposus extrusion." (PMID 41150106, 2025).
white matter hyperintensities (2 papers, 2024 to 2025). "We investigated the association between white matter hyperintensities (WMH) severity and fluid biomarkers, including cerebrospinal fluid (CSF) neurofilament light chain and plasma placental growth factor (PlGF) levels." (PMID 41154596, 2025).
Acute encephalopathy (1 paper, 2023). "Further, in patients needing a lumbar puncture to evaluate acute encephalopathy, biomarkers identified in cerebrospinal fluid such as neurofilament light chain (NfL) and inflammatory cytokines may be of some utility." (PMID 37427016, 2023).
Charcot-Marie-Tooth disease type 2 (1 paper, 2019). "Mutations in the NEFL gene cause Charcot-Marie-Tooth disease type 2 (CMT2) and mutations of NEFH and neurofilament hyperphosphorylations are associated with ALS, AD, and PD." (PMID 31252669, 2019).
GM2 gangliosidosis (1 paper, 2025). A group of recessively inherited diseases characterized by the intralysosomal accumulation of G(M2) GANGLIOSIDE in the neuronal cells. "Novel markers, including neurofilament light chain (NfL) and oxysterols, are under investigation for NPC and GM2 gangliosidosis, with potential relevance to disease monitoring and progression, particularly in adult-onset phenotypes." (PMID 40869962, 2025).
leukodystrophies (1 paper, 2024). "Moreover, non-disease-specific and non-invasive biomarkers of neuroaxonal and astroglial injury, such as neurofilament light chain (NfL) and glial fibrillary acidic protein (GFAP) levels, can be widely applicable across leukodystrophies." (PMID 37755460, 2024).
liposarcoma (1 paper, 2018). A usually painless malignant tumor that arises from adipose tissue. "In addition, fused in sarcoma/translocated in liposarcoma (FUS/TLS), another ALS-associated protein, has been shown to bind to murine NEFL, NEFM and NEFH transcripts." (PMID 30029677, 2018).
lung carcinoma (1 paper, 2020). "In this study, we firstly explored if serum neurofilament light chain (NfL) levels are elevated in lung cancer patients with brain metastases compared with lung cancer patients without brain metastases." (PMID 33023150, 2020). "Neurofilament light chain (NfL) is a neuron-specific protein released after neuronal decay, and we evaluated blood-borne NfL as a biomarker in 43 lung cancer patients with brain metastases and 25 without brain metastasis." (PMID 33023150, 2020).
lymph node metastasis (1 paper, 2012). "NEFL mRNA was expressed in all of the 14 lymph node metastasis samples, and expression ranged from 5.52×10−8 to 9.46×10−6." (PMID 22319610, 2012). "Moreover, NEFL mRNA was expressed in 97% primary cancer tissues and 100% lymph node metastasis samples, and the difference of NEFL mRNA levels between the malignant and normal breast tissues was statistically significant (P<0.001)." (PMID 22319610, 2012).
myasthenia gravis (1 paper, 2022). Myasthenia gravis (MG) is a rare, clinically heterogeneous, autoimmune disorder of the neuromuscular junction characterized by fatigable weakness of voluntary muscles. "This study aimed to evaluate the association of neurofilament light chain (Nfl) with neuromuscular destruction and disease severity in the serum of patients with myasthenia gravis (MG)." (PMID 36712429, 2022).
oligodendroglioma (1 paper, 2020). A well-differentiated (WHO grade II), diffusely infiltrating neuroglial tumor, typically located in the cerebral hemispheres. "In our cohort, tumors expressing canonical neuronal markers like neurofilament (NEFL, NEFM, and NEFH) and synaptophysin (SYP) were significantly localized within the expression space of oligodendrogliomas (q-value < 0.015)." (PMID 32732999, 2020).
pancreatitis (1 paper, 2024). Inflammation of the pancreas. "We confirm here that early loss of HTT leads to subcortical calcification, which is preceded by induction of circulating neurofilament light chain levels, but find no pancreatitis." (PMID 39054288, 2024).
Retinal atrophy (1 paper, 2022). A nonspecific term denoting wasting, especially as a result of degeneration, of the retinal pigment epithelium (RPE) and neurosensory retinal cells. "Both retinal atrophy measured through optical coherence tomography and plasma neurofilament light chain (NfL) levels are markers of neurodegeneration, but their relationship is unknown." (PMID 35243826, 2022).
rheumatic diseases (1 paper, 2023). "Serum samples of 88 patients with different rheumatic diseases were analyzed for the presence of anti-NR2 antibodies and Neurofilament light chain (NfL) protein." (PMID 36834970, 2023).
SARS-CoV infection (1 paper, 2020). "Neurofilament triplet L protein (NEFL) gene can be downregulated in the SARS-CoV infection, while NEFL gene is upregulated in Zika virus infected cells." (PMID 32754004, 2020).
Senile plaques (1 paper, 2025). Senile plaques are extracellular deposits of amyloid in the gray matter of the brain. "Additionally, AD‐specific markers, such as senile plaques and serum neurofilament light chain (NfL) levels, were detected using Thioflavin S staining and single‐molecule array technology, respectively." (PMID 40205810, 2025).
Tinnitus (1 paper, 2025). Tinnitus is an auditory perception that can be described as the experience of sound, in the ear or in the head, in the absence of external acoustic stimulation. "However, in other conditions unrelated to tinnitus, the presence of specific markers—such as neurofilament light chain, correlated with brainstem and peripheral nerve damage—has been proposed." (PMID 41283492, 2025).
triple-negative breast carcinoma (1 paper, 2021). An invasive breast carcinoma which is negative for expression of estrogen receptor (ER), progesterone receptor (PR), and human epidermal growth factor receptor 2 (HER2). "NEFL is also considered an immune gene associated with prognosis in triple-negative breast cancer." (PMID 33790966, 2021).
Wilms tumor (1 paper, 2019). An embryonal neoplasm characterized by the presence of epithelial, mesenchymal, and blastema components. "Given the important tumor-suppressing role of the NEFL gene, we investigated the potential association between these three NEFL polymorphisms and Wilms' tumor susceptibility in a Chinese population including 145 cases and 531 controls." (PMID 31057612, 2019). "In summary, our present data indicated the NEFL gene polymorphisms may associate with Wilms' tumor susceptibility in the Chinese population." (PMID 31057612, 2019).